VPS13A (vacuolar protein sorting 13 homolog A)
Diseases named in the same sentence as VPS13A in open-access papers (continued):
Sharing a sentence is not in itself a finding about the gene and the disease.
infection (3 papers, 2017 to 2024). The state of being infected such as from the introduction of a foreign agent such as serum, vaccine, antigenic substance or organism. "Although Vps13a KO brains in the C57BL/6 strain were almost normal under specific-pathogen-free laboratory conditions, the phenotypic severity may be altered by environmental factors such as stress, infection, and food." (PMID 39063018, 2024).
VPS13A also shares sentences with these, for which no sentence is quoted: Cohen syndrome (4 papers); Parkinsonism (3); tumor (3); breast cancer (2); cerebellar ataxia (2); Cognitive impairment (2); Orofacial dyskinesia (2); aceruloplasminemia (1); alopecia (1); Alzheimer disease (1); autosomal recessive disease (1); chronic pancreatitis (1); diabetes (1); Hepatic steatosis (1); Huntington disease-like 2 (1); invasive breast carcinoma (1); Lesch-Nyhan syndrome (1); lymph node metastasis (1); neuroferritinopathy (1); Niemann‐Pick type C disease (1); pancreatic cancer (1); polyneuropathy (1); rhabdomyosarcoma (1); spastic ataxia (1); Stroke (1); triple-negative breast carcinoma (1); Wilson disease (1).